PKD1P3 (polycystin 1, transient receptor potential channel interacting pseudogene 3)
Synonyms: HG3
Gene: Transcribed unprocessed pseudogene on chromosome 16 (14,911,551 to 14,935,708, forward strand). Ensembl gene ENSG00000183458.
Diseases named in the same sentence as PKD1P3 in open-access papers:
PKD1P3 is named in the same sentence as 4 diseases in open-access papers, as found by Europe PMC text mining. Sharing a sentence is not in itself a finding about the gene and the disease.
PKD1P3 shares sentences with these, for which no sentence is quoted: breast carcinoma (1 paper); cancer (1); COVID-19 (1); ovarian carcinoma (1).